STYK1 (STY kinase 1)
Diseases named in the same sentence as STYK1 in open-access papers (continued):
Sharing a sentence is not in itself a finding about the gene and the disease.
cancer (15 papers, 2009 to 2025). A tumor composed of atypical neoplastic, often pleomorphic cells that invade other tissues. "To explore the molecular mechanisms underlying lnc-STYK1-2-regulated cancer development, we then analyzed the differentially expressed genes in 5637 and T24 cells with silenced lnc-STYK1-2 expression by RNA sequencing." (PMID 34332611, 2021). "The diagnostic implication of STYK1 mRNA has been demonstrated in cancers of breast, lung and colorectum." (PMID 25884558, 2015). "PTPRU, IKBKE, STYK1, and CENPO are implicated in key biological pathways relevant to cancer biology, including cell signaling, cell migration, and inflammation, further supporting their relevance in tumorigenesis." (PMID 39684488, 2024). "We found that chemical inhibition of EGFR combined with the siRNA-mediated knockdown of STYK1 led to a significant decrease in cancer cell viability and anchorage-independent cell growth." (PMID 35840561, 2022). "STYK1 is overexpressed in various cancer types including NSCLC, and immunohistochemical analyses in tumors have shown that STYK1 is more expressed in NSCLC samples compared to adjacent non-cancerous tissues." (PMID 35840561, 2022). "We found STYK1 as a potential target for a combination therapy with EGFR inhibition in NSCLC and demonstrate that STYK1 downregulation improves the anti-cancer effects of EGFR TKI in vitro." (PMID 35840561, 2022). "One month after the cancer cell injection, we showed that tumors derived from both T24 and 5637 cells with sh-lnc-STYK1-2 in nude mice were significantly larger than those in the sh-NC group." (PMID 34332611, 2021). "The patients were divided to two groups (low STYK1 and high STYK1) according to median of STYK1 expression in cancer tissues samples." (PMID 27628214, 2016). "Due to the potential significance of STYK1 in cancer biology, its clinical relevance in human malignancies has aroused increasing attention." (PMID 25884558, 2015). "The novel oncogene STYK1/NOK plays critical roles in cancer development." (PMID 36506394, 2022). "Overall, depletion of STYK1 from cancer cells may diminish persistence mechanisms elicited by EGFR inhibition, such as FGF1 upregulation, and in that way reduce/eliminate the pool of drug tolerant cells in which constitutive, genomic resistance may arise." (PMID 35840561, 2022). "Interestingly, it has been previously reported that STYK1 can act as a scaffold to enhance the phosphorylation of GSK3β through activated Akt, which likely promotes cancer cell survival." (PMID 35840561, 2022). "STYK1 (serine/threonine/tyrosine kinase 1), also known as NOK (novel oncogenic kinase), is a member of the PTK (protein tyrosine kinase) protein subfamily closely associated with the initiation and progression of multiple human cancers." (PMID 34332611, 2021). "Previous studies reported that STYK1 promotes Akt phosphorylation in cancer cells, and we also found STYK1 overexpression could increase the p-Akt levels in NSCLC cells." (PMID 31164631, 2019). "The significance and prognostic value of STYK1 were also demonstrated in other types of cancers." (PMID 29340057, 2017). "Despite evidence of STYK1 acting as an oncogene and being involved in a variety of cancers, the role of STYK1 in regulating HCC metastasis and EMT remains unclear." (PMID 27628214, 2016). "Most previous studies focused on the expression of STYK1 in cancer tissues." (PMID 27628214, 2016). "We then investigated if STYK1 enhanced cancer cell metastasis in vivo." (PMID 27628214, 2016). "Given the importance of the MAPK, PI3K, Akt and GSK-3beta signalings in the pathogenesis of human cancers, these molecular findings may, in part, account for the oncogenic property of STYK1 protein." (PMID 25884558, 2015). "Our data showed higher expression of STYK1 in cancer tissues versus normal or benign." (PMID 19845955, 2009).
cancer (continued). "Furthermore, STYK1’s mechanism of promoting cancer cell mobility and epithelial-mesenchymal transition (EMT) was found to be via the MEK/ERK and PI3K/AKT pathways, resulting in increased expression of mesenchymal protein markers: snail, fibronectin, and vimentin, and decreased E-cadherin expression." (PMID 27628214, 2016). "STYK1 depletion significantly reduced RTCA-measured cell index, reflecting reduced cancer cell proliferation capacity." (PMID 40588478, 2025). "These phenomena suggested that the STYK1 overexpression promoted the NSCLC cells’ epithelial–mesenchymal transition (EMT) potential, which plays important roles on cancer metastasis." (PMID 31164631, 2019). "To investigate the expression of STYK1 in NSCLC, we first performed data-mining to analyze the gene expression profiles of STYK1 between cancer and normal tissues." (PMID 31164631, 2019). "Previous studies showed that aberrant Serine/threonine/tyrosine kinase 1 (STYK1, also known as NOK) or/and E-cadherin were involved in the progression of some types of human cancers." (PMID 29340057, 2017). "Our results suggest the possible roles of GEN1, KRIT1, CENPF, STYK1, and Sam68/KHDRBS3 in promoting cancer cell proliferation, and these findings may provide a potential therapeutic target to control mast cell malignancy." (PMID 35884586, 2022). "MEK/ERK and PI3K/AKT signaling pathways play important roles in migration, invasion, and metastasis of cancer by regulating EMT; therefore, we investigated if STYK1 was capable of promoting migration, invasion, and EMT via the MEK/ERK and PI3K/AKT pathway in HCC cells." (PMID 27628214, 2016). "Several studies reported that STYK1 overexpression could promote cancer cell proliferation, but the action of STYK1 on NSCLC cell proliferation has not been previously verified." (PMID 31164631, 2019). "Only normal or benign, and one cancer tissue were STYK1-negative." (PMID 19845955, 2009).
infection (2 papers, 2021 to 2024). The state of being infected such as from the introduction of a foreign agent such as serum, vaccine, antigenic substance or organism. "The significant downregulation of lnc-STYK1-2 expression in T24 and 5637 cells caused by infection with recombinant lentivirus vectors ligated with shRNA sequences was first confirmed by qRT-PCR." (PMID 34332611, 2021).
STYK1 also shares sentences with these, for which no sentence is quoted: adenocarcinoma (1 paper); brain glioblastoma (1); colorectal adenocarcinoma (1); gastric cancer (1); leprosy (1); leukemia (1); liver cancer (1); pancreatic ductal adenocarcinoma (1); prostate adenocarcinoma (1).